XCL1 (X-C motif chemokine ligand 1)
Diseases named in the same sentence as XCL1 in open-access papers (continued):
Sharing a sentence is not in itself a finding about the gene and the disease.
Cerebral ischemia (2 papers, 2021 to 2024). Restriction of arterial blood supply to the brain associated with insufficient oxygenation to support the metabolic requirements of the tissue. "There are few studies on XCL-1 in cerebral ischemia, and the role of XCL-1 in neurological damage during the course of VaD remains to be investigated subsequently." (PMID 39206161, 2024). "In the CCH phase, prolonged low levels of CCL11 are detrimental to the prognosis of patients with cerebral ischemia; CX3CL1, XCL-1 and CCL2/MCP-1 exert neuroprotective effects." (PMID 39206161, 2024). "Inhibition of CXCL5, CXCL13, XCL-1,and CCL2/MCP-1 during the cerebral ischemia/reperfusion (CI/R) phase of VaD holds promise as a therapeutic strategy to mitigate microglial activation and minimize neurological injury." (PMID 39206161, 2024). "During the CI/R phase, CXCL5 recruits inflammatory cytokines at sites of cerebral ischemia and disrupts cerebral vasculature; activated cerebral vasculature can exacerbate cerebral neuronal injury by expressing CXCL13; meanwhile, XCL-1 and CCL2/MCP-1 promote neuronal apoptosis." (PMID 39206161, 2024).
co-infection (2 papers, 2021 to 2023). "In addition, CCL4, CXCL1, and CXCL2 expression in the co-infection group was highly significant, while CX3CL1 and XCL1 expression was equivalent to that in mock control." (PMID 33968006, 2021).
HIV-1 infection (2 papers, 2013 to 2019). The type species of lentivirus and the etiologic agent of acquired immunodeficiency syndrome (AIDS). "We observed that both WT and W55D XCL1 were equally effective at blocking HIV-1 infection in heparitinase-treated and -untreated cells, while in contrast the CC3 variant remained inactive in both conditions." (PMID 24385911, 2013). "In this study, we report the characterization of the CD8+ T cell-derived C-chemokine, XCL1, as a novel, broad-spectrum inhibitor of HIV-1 infection." (PMID 24385911, 2013). "Whether and to what extent endogenous XCL1 contributes to the mechanisms of virus control during the course of HIV-1 infection is presently unknown." (PMID 24385911, 2013). "In a similar manner, this study could be a first step toward determining the potential physiological role of XCL1 in HIV-1 infection." (PMID 24385911, 2013). "XCL1 potently inhibited HIV-1 infection irrespective of coreceptor specificity, as it was equally effective on strains specific for CXCR4 (X4; IIIB) and CCR5 (R5; BaL)." (PMID 24385911, 2013).
injury (2 papers, 2020 to 2025). Damage inflicted on the body as the direct or indirect result of an external force, with or without disruption of structural continuity. "For example, studies have shown elevated transcript or protein levels of CXCL5, CX3 CL1, and XCL1 in neuronal cell bodies following nerve injury." (PMID 40217284, 2025). "Based on the available literature and our results, we suggest that XCL1 deserves further study, especially because XCR1 and ITGA9 seem to be important novel targets with beneficial properties for pharmacological intervention after brain injury." (PMID 33185818, 2020).
myeloma (2 papers, 2018 to 2023). "In murine tumor models, injection of XCL1-expressing myeloma cells in Balb/c and nude mice resulted in tumor regression." (PMID 38026637, 2023). "Using a murine myeloma line as an in vitro model system and also employing heat-shock experiments, we consistently observed binding of XCL1 to cells characterized as “necrotic” or “apoptotic,” based on the use of Annexin V and DAPI." (PMID 30619244, 2018).
neuropathy (2 papers, 2020 to 2022). A disorder affecting the nervous system that manifests with pain, tingling, numbness, and/or muscle weakness. "Moreover, our data suggest that minocycline, a widely used antibiotic that affects many intracellular pathways, can reveal high analgesic potential in neuropathy by influencing more immune factors than was previously thought, including XCL1." (PMID 36618360, 2022). "It remains unknown how XCR1 and ITGA9 are involved in nociceptive transmission; however, their role seems to be extremely important in neuropathy, as our previous research proved the strong pronociceptive properties of their ligand, XCL1, in naive animals." (PMID 36618360, 2022). "Additionally, our results indicated that the mechanisms of minocycline analgesic action in neuropathy may also involve the decrease in the pronociceptive XCL1." (PMID 36618360, 2022). "Therefore, we hypothesized that in neuropathy, XCL1 acts through neuronally localized receptors." (PMID 36618360, 2022). "Importantly, we observed for the first time that minocycline treatment also lowered the protein level of XCL1 in the CCI-induced neuropathy model, which might be considered behind the additional mechanism of its beneficial effects in neuropathy." (PMID 36618360, 2022). "Moreover, we have previously shown that metamizole diminishes XCL1 expression at the spinal cord level in a model of neuropathy; however, our current results indicate that this is not a case at the DRG level." (PMID 32691345, 2020).
oral cancer (2 papers, 2018 to 2020). "The effect of XCL1 on ERK activation in MDA-MB-231 cells was similar to that in H357 and SCC4 oral cancer cells." (PMID 33374849, 2020).
ovarian carcinoma (2 papers, 2013 to 2014). A malignant neoplasm originating from the surface ovarian epithelium. "Chemokines lymphotactin 1 and lymphotactin 2, XCL1 and XCL2, respectively, bind and activate XCR1, leading to increased proliferation and migration of ovarian cancer cells that express XCR1." (PMID 24384839, 2013). "The ovarian carcinoma cells themselves express XCL1, and XCL2 is detected in the ascites from ovarian carcinoma, suggesting that XCL/XCR1-driven cell proliferation and migration could contribute to growth and expansion of peritoneal metastasis." (PMID 24384839, 2013).
prostate carcinoma (2 papers, 2021 to 2025). A carcinoma that arises from epithelial cells of the prostate gland. "XCL1 has been less studied in prostate cancer, but existing studies have demonstrated that XCL1 is involved in the antitumor process and correlates with a good prognosis of the cancer." (PMID 40149637, 2025). "These cells showed increased expression of CCL5, XCL1, and XCL2 in prostate cancer, with the potential to recruit cDC1." (PMID 34936871, 2021).
Sepsis (2 papers, 2025). Sepsis is defined as life-threatening organ dysfunction caused by a dysregulated host response to infection. "We also screened adult sepsis datasets to find genes specific to pediatric cases, ultimately validating XCL1 as a key gene." (PMID 40453217, 2025). "This study suggests that XCL1 is crucial in understanding pediatric sepsis etiology and its molecular mechanisms." (PMID 40453217, 2025). "sc-RNA seq and assignment into two types of NK cells confirmed that heatstroke and sepsis were associated with lower number of NK cells than that in the other two groups, rather than affecting the relative abundance of CD56bri NK cells (NKG7+XCL1+) and CD56dim NK cells (NKG7+FGFBP2+)." (PMID 40084252, 2025).
triple-negative breast carcinoma (2 papers, 2020 to 2024). An invasive breast carcinoma which is negative for expression of estrogen receptor (ER), progesterone receptor (PR), and human epidermal growth factor receptor 2 (HER2). "It was reported that the overexpression of X-C motif chemokine receptor 1 (XCR1), a specific receptor for chemokine X-C motif chemokine ligand 1 (XCL1), stimulates the migration of MDA-MB-231 triple-negative breast cancer cells." (PMID 33374849, 2020).
Achalasia (1 paper, 2023). A disorder of esophageal motility characterized by the inability of the lower esophageal sphincter to relax during swallowing and by inadequate or lacking peristalsis in the lower half of the body of the esophagus. "We show C1QC+ macrophages and tissue-resident memory T cells (TRM), especially ZNF683+ CD8+ TRM and XCL1+ CD4+ TRM, are significantly expanded and localized surrounding the myenteric plexus in the LES tissue of achalasia." (PMID 37542039, 2023). "We found TRM showed more expansions in achalasia than those in controls, especially in ZNF683+ CD8+ TRM and XCL1+ CD4+ TRM." (PMID 37542039, 2023). "Metascape analysis of marker genes of each TRM subcluster showed that ZNF683+ CD8+ TRM and XCL1+ CD4+ TRM, the most common types in achalasia, were enriched mainly in adaptive immune and lymphocyte activation." (PMID 37542039, 2023). "Among the TRM subclusters, XCL1+ CD4+ TRM (Th5) and ZNF683+ CD8+ TRM (Tc5), expanded remarkably in achalasia compared with controls." (PMID 37542039, 2023). "We found TRM were increasingly infiltrated in the LES tissue in achalasia and mainly restricted to the area surrounding the myenteric plexus, especially ZNF683+ CD8+ TRM and XCL1+ CD4+ TRM." (PMID 37542039, 2023).
acute lymphoblastic leukemia (1 paper, 2020). Leukemia with an acute onset, characterized by the presence of lymphoblasts in the bone marrow and the peripheral blood. "Moreover, a higher serum XCL1 level at diagnosis and its progressive decreases during chemotherapy are good prognostic markers for patient survival in acute lymphoblastic leukemia." (PMID 33374849, 2020).
Arthritis (1 paper, 2017). Inflammation of a joint. "As one example, Iwamoto and co-workers have described the increased expression of six CC chemokines, five CXC chemokines, XCL1, and CX3CL1 in the synovial tissues of rheumatoid arthritis patients, compared to other forms of arthritis or healthy controls." (PMID 28178200, 2017).
asthma (1 paper, 2023). "In addition, we recently reported that iNKT cells contribute to the development of asthma by secreting X-C motif chemokine ligand-1, which recruits conventional X-C motif chemokine receptor 1-expressing type-1 dendritic cells into the lungs: this then stimulates the Th2 responses that drive asthma." (PMID 37917548, 2023).
breast tumors (1 paper, 2017). "Finally, lower levels of several pro-inflammatory cytokines (IL1B, IL10, IL12, IL6, IL8, TNF), NK cell metagenes (NCR1, XCL1), cytolytic enzymes (GZMA, GZMB, PRF) and type I IFN-induced genes were also observed in IL-1R8 high breast tumors." (PMID 28533483, 2017).
cerebral infarction (1 paper, 2025). An ischemic condition of the brain, producing a persistent focal neurological deficit in the area of distribution of the cerebral arteries. "Our study observed that the number of NK cells in the atherosclerotic plaque tissue of the internal carotid artery in cerebral infarction increased, and endocytosis was significantly enriched in the NK_XCL1 subpopulation." (PMID 40303468, 2025).
colorectal tumor (1 paper, 2022). "Murine colorectal tumor cell lines (CT26 and MC38) stably overexpressing mouse C-C motif chemokine ligand 3 (CCL3), CCL19, CCL21, and X-C motif chemokine ligand 1 (XCL1) were established by lentiviral transduction." (PMID 36654820, 2022).
endometriosis (1 paper, 2021). The growth of functional endometrial tissue in anatomic sites outside the uterine body. "We found that the gene expression of GZMB was significantly down-regulated (0.546 ± 0.079 vs. 1.300 ± 0.278, P = 0.0149) while XCL1 was up-regulated (3.889 ± 0.466 vs. 1.672 ± 0.238, P = 0.0006) in endometriosis compared to that of control groups." (PMID 34039410, 2021). "The highly differential genes between the two groups showed that C–C motif chemokine ligand 3 (CCL3) and X-C motif chemokine ligand 1 (XCL1) were significantly elevated in endometriosis while cytotoxic molecules including GNLY, GZMB and GZMH were significantly down-regulated." (PMID 34039410, 2021).
hepatocellular carcinoma (1 paper, 2025). A malignant tumor that arises from hepatocytes. "Here, we conducted comprehensive analyses based on multiple scRNA-seq datasets to identify the presence of XCL1+ CD8+ T cells in hepatocellular carcinoma (HCC) tumor microenvironment." (PMID 41426973, 2025).
infertile (1 paper, 2017). "Recent experimental results showed that XCL1 was significantly down-regulated in the endometrium of obese infertile patients, suggesting that XCL1 expression may exhibit depot-specific characteristics." (PMID 29141038, 2017).
Listeria infection (1 paper, 2019). "Interestingly, only CD8+ T cell subsets isolated at 12 and 24 h post-Listeria infection (T.CD8+EFF, OT-I & LIS-12 and 24 h) showed a significant correlation, suggesting that XCL1-producing CD8+ T cells have an immature early effector phenotype." (PMID 31130969, 2019).
liver cancer (1 paper, 2023). An epithelial or non-epithelial malignant neoplasm that arises from the liver. "In b_ILC1-XCL1, which is similar to the ILC2a cells found in liver cancer, genes such as XCL1, TCF7, and CD74 were highly expressed." (PMID 37762493, 2023).
lymphoproliferative disorder (1 paper, 2023). "XCL1 is downregulated in human Sezary syndrome, but was expressed by T-3B cells in a case report of a patient with concurrent T and B cell cutaneous lymphomas and by T cells in a patient with lymphoproliferative disorder." (PMID 38026637, 2023).
ovarian tumor (1 paper, 2020). "In addition, XCL1 expression is related to the number of tumor-infiltrating CD8+ T-cells and PD-L1 expression on ovarian tumor cells, which indicated that XCL1 might be a biomarker for anti-PD1/PD-L1 immunotherapy." (PMID 32508884, 2020).
peripheral nerve injury (1 paper, 2021). Injury to a peripheral nerve. "This study identified a novel role for XCL1/XCR1 in nociceptive processing and suggests a pronociceptive role for the XCL1/XCR1 axis in peripheral nerve injury and neuropathic pain." (PMID 35295531, 2021).
pulmonary fibrosis (1 paper, 2023). Chronic progressive interstitial lung disorder characterized by the replacement of the lung tissue by connective tissue, leading to progressive dyspnea, respiratory failure, or right heart failure. "The lack of changes in Cxcl13, Ccl11, Ccl19, Xcl1, and Cxcl5 mRNA levels may be due to differences in bleomycin-induced pulmonary fibrosis and IPF, although models of bleomycin-induced pulmonary fibrosis are the most common experimental models for investigating IPF." (PMID 37122736, 2023).
renal carcinoma (1 paper, 2024). A carcinoma arising from the epithelium of the renal parenchyma or the renal pelvis. "Interestingly, the Human Protein Atlas data also provided evidence of XCL1-overexpressing tumour cells in a number of cancer types, and this overexpression is significantly correlated with a shorter overall survival rate in patients with colorectal and renal cancer." (PMID 39419971, 2024).
Splenomegaly (1 paper, 2015). Abnormal increased size of the spleen. "We observed a dramatic increase in the expression of several proinflammatory markers such as Il17a, Ifnγ, Tnfα, IL-1β and Ifitm1, and chemokines such as Ccl1, Cxcl10, Ccl22 and Xcl1, in ATMINΔLNBS1ΔL mice displaying splenomegaly, compared to the other genotypes." (PMID 26544571, 2015).
Stroke (1 paper, 2025). Sudden impairment of blood flow to a part of the brain due to occlusion or rupture of an artery to the brain. "The role of XCL1 in stroke remains unreported and requires further investigation." (PMID 40303468, 2025).
tumor (146 papers, 2007 to 2026). "In this study, we specifically targeted XCR1, expressed on the surface of cDC1, and the DNA vaccine that fused its ligand-XCL1 with two tumor-associated antigens showed stronger immunogenicity and antitumor effects in mice." (PMID 38339158, 2024). "We found that XCL1 expression by intratumoral CD8+ T cells was upregulated in hsBCL9z96-treated CT26 tumor-bearing mice and MC38 tumor-bearing Bcl9/Bcl9l deficiency mice." (PMID 38811552, 2024). "Another tumor-infiltrating XCL1high NK subcluster that expressed a high level of genes associated with the recruitment of DCs (XCL1, XCL2, and FLT3LG) was more highly detected in the PD-1+SMI than in the PD-1 group." (PMID 37430270, 2023). "XCL1 expression on tumor cells was significantly associated with the number of tumor-infiltrating CD8-positive T cells and PD-L1 expression on tumor cells." (PMID 32115573, 2020). "The loss of Flt3L, CCL5, and XCL1 secretion by tumor-infiltrating NK cells impacts recruitment and survival of cross-presenting DCs, and correlates with increased tumor growth and responsiveness to anti-PD1 therapy." (PMID 32121071, 2020). "A significant association between XCL1 expression and a high tumor infiltration rate of CD8-positive T cells was observed in MCT-SCC/ASCs (p = 0.0078)." (PMID 32115573, 2020). "In NK cell-depleted mice, Ptgs1/Ptgs2−/− BRAFV600E tumors expressing XCL1 grew more slowly than mock-transduced cells, suggesting that XCL1-mediated recruitment of cDC1 can partially compensate for the loss of tumor immune control caused by NK cell ablation." (PMID 29429633, 2018). "Moreover, we identified expanded XCL1+ T‐cell clusters associated with tumor mutational burden high status." (PMID 34185431, 2021). "Therefore, we investigated the associations of XCL1 expression on tumor cells with tumor infiltration of CD8-positive T cells and PD-L1 expression on tumor cells, which is known as a biomarker for immune checkpoint inhibitors." (PMID 32115573, 2020). "The usage of XCL1 variants engineered to enhance receptor stability and chemotactic activity was reported to further improve anti-tumor immune response and could provide a rational for future translational developments." (PMID 32486257, 2020). "Similarly, adenoviral delivery of XCL1 and tumor-associated antigens to DC increases IL-2 and IFNγ production by NK and T cell populations." (PMID 30979057, 2019). "Furthermore, we also found that both XCL1 and XCL2 had much more elevated expression in patient tumour samples compared to their matched normal (P < 0.0001), and within tumour samples, high XCL1 expression was significantly associated with worse overall survival." (PMID 39419971, 2024). "Once internalized, the plasmids expressed in tumor cells produce XCL1 and FLT3L, significantly promoting the recruitment and differentiation of cDC1." (PMID 41178526, 2026). "Tumor-infiltrating CD4+ TRMs exert helper antitumor effects by secreting the chemokine XCL1 to recruit conventional type 1 dendritic cells (cDC1s), facilitating antigen presentation and priming cytotoxic T lymphocyte responses." (PMID 41486351, 2026). "Following uptake, tumor cells are reprogrammed into in situ cytokine factories that continuously secrete XCL1 and FLT3L, which effectively recruit and differentiate cDC1s within the tumor microenvironment." (PMID 41178526, 2026). "Subsequently, these tumor cells are reprogrammed into in situ cytokine factories that continuously secrete XCL1 and FLT3L, which effectively recruit and differentiate cDC1s within the tumor microenvironment." (PMID 41178526, 2026). "Due to the interaction between XCL1 in CD8+ T cells and XCR1 in DCs playing the key role in anti-tumor efficacy, the number of XCL1+ CD8+ T cells and XCR1+ DCs in microenvironment directly determined the prognosis of HCC patients." (PMID 41426973, 2025).